INS (insulin)
Diseases named in the same sentence as INS in open-access papers (continued):
Sharing a sentence is not in itself a finding about the gene and the disease.
Insulin resistance (continued). "SREBP transcription factors are major players in lipid metabolism and possibly insulin resistance, whereas GSK3 phosphorylates SREBP in the absence of insulin and AKT signaling, leading to its degradation." (PMID 31159854, 2019). "Another report demonstrated that 5 is a non-competitive PTP1B inhibitor in vitro and improved insulin resistance by inhibition of PTP1B and stimulation of insulin signaling pathway in insulin-resistant HepG2 cells." (PMID 31121891, 2019). "In the present study we found that WD-exposure of 22 month-old mice did not alter insulin and glucose levels in the plasma, resulting in a similar HOMA-index suggesting that upon old age, WD-exposure does not induce insulin resistance." (PMID 30860940, 2019). "A reduction of GLUT4 expression is related to the development of insulin resistance, since transgenic mice lacking GLUT4 were shown to have insulin insensitivity." (PMID 31635074, 2019). "It is noteworthy that velagliflozin did not affect insulin resistance per se in this study, with no change in CGIT measurements of glucose or insulin concentrations over time, or in the number of ponies classified as IR according to the test." (PMID 30808423, 2019). "Correspondingly, DKO mouse livers exhibited strong insulin resistance, and hepatocytes from DKO mice did not activate AKT in response to insulin." (PMID 31754457, 2019). "In the present study, CTRP5 levels showed a weak and negative correlation with insulin, FBG, and insulin resistance." (PMID 29964236, 2019). "The majority of studies published to‐date have used HOMA‐IR to quantify insulin resistance in CHC31, 32 which only provides a global, systemic measure of insulin sensitivity and does not discriminate between hepatic and peripheral effects." (PMID 30586166, 2019). "Brain insulin resistance in DM1 is currently an unexplored field, and direct evidence for altered brain insulin signaling in DM1 is lacking." (PMID 31849810, 2019). "The results of this study showed that the PCOS group had significantly higher levels of insulin, insulin resistance, glucose, all plasma lipids except HDL-C, compared to the healthy controls, while insulin secretion was not different." (PMID 30131073, 2018). "Further analysis indicated that the relation between FM distribution and insulin resistance was stronger in women than in men; in particular, DXA-derived %LFM was a stronger correlate of insulin sensitivity in women than in men independent of age/BMI/WC." (PMID 29531527, 2018). "In contrast, low abuse youth showed hyperinsulinemia and more insulin resistance than high abuse youth, and their higher OGTT insulin areas under the curve correlated with more negative insula-precuneus connectivity." (PMID 30622489, 2018). "Insulin resistance as indicated by the higher HOMA-IR was significantly more in the PCOS compared to the controls, but the insulin secretion as judged from the value of HOMA-S was not different between the two groups." (PMID 30131073, 2018). "We found no elevation of two species of DAG in the insulin resistant obese group, nor did the levels of the same DAG species increase with insulin resistance induced by prolonged fasting in the lean group." (PMID 30183740, 2018). "It is thus possible that besides a theoretically more insulin-sensitive WAT, other tissues have developed insulin resistance in the absence of Malat1, although this would require additional experimental characterization." (PMID 29746487, 2018). "The observed reduction of insulin concentration and insulin resistance by the Okinawa-based Nordic diet seem to be interconnected with lower levels of adipokines, although the close relation between resistin and insulin resistance found in other studies could not be confirmed in the present study." (PMID 29599686, 2018). "Insulin failed to phosphorylate IR, PKB, and GSK3β in KK-Ay, reflecting the severe insulin resistance of these mice." (PMID 29768504, 2018).
Insulin resistance (continued). "ET helps to reduce fasting glycaemia, insulin resistance (HOMA 2-IR lowered below 1.85) and improves muscular insulin sensitivity (MISI) without modify hepatic resistance (HIRI)." (PMID 30305835, 2018). "Notably, by performing insulin-tolerance tests (ITTs) and glucose-tolerance tests (GTTs), dietary betaine supplementation could be observed for improvement of obesity and non-obesity induced insulin resistance." (PMID 29373534, 2018). "However, exchanging S307 in IRS1 to a nonphosphorylatable amino acid fails to protect against the development of obesity-induced insulin resistance, and instead impairs insulin sensitivity, indicating that the impact of TNFα on insulin signaling might be context- and cell-type-dependent." (PMID 30591653, 2018). "The presence of insulin resistance in the absence of frank obesity, elevated NEFA or hyperinsulinaemia raises the possibility that changes to insulin sensitivity in these mice are programmed during early life." (PMID 30043179, 2018). "On the other hand if we assume e1 to be large i.e. most of the variation in FG is due to random error or effects independent of insulin action, HOMA-IR is poorly correlated with true insulin resistance, the correlation coefficient declining to 0.2." (PMID 30307959, 2018). "Another interesting link between insulin resistance and Aβ accumulation is IDE, which is responsible for not only the degradation of excess insulin, but also the degradation of Aβ." (PMID 30249283, 2018). "In some studies conducted with 500 mg/day of BC insulin, glucose and HOMA-IR (homeostasis model assessment-insulin resistance) values did not change." (PMID 28704936, 2017). "We aimed to determine the effect of pegvisomant, a GH receptor antagonist, on insulin resistance, endogenous glucose production (EGP) and lipolysis in insulin resistant non-diabetic men." (PMID 28713554, 2017). "Thus, the results obtained from in vitro and in vivo studies, strengthen the hypothesis that the higher basal activation of the insulin signalings may be accompanied by a lack of further stimulation of the pathways and hence may contribute to insulin resistance." (PMID 28915272, 2017). "Second, insulin resistance was determined by HOMA-IR calculated with fasting glucose and fasting insulin levels rather than the hyperinsulinemic euglycemic clamp, which remains the “gold standard” for accurately determining insulin resistance." (PMID 29390354, 2017). "Third, insulin resistance was not evaluated using euglycemic/hyperinsulinemic clamp, nonetheless HOMA-IR index has proven to be a reliable measurement of insulin sensitivity." (PMID 28969085, 2017). "While this early lipolysis occurs in the absence of insulin resistance in the adipose tissue, the released FFA can rapidly initiate hepatic insulin resistance, in part by activating PKCδ-mediated pathways." (PMID 28184213, 2017). "As expected, type 2 diabetic patients with abdominal obesity had higher postprandial AUCs for insulin and HOMA-IR than those without abdominal obesity and controls, suggesting greater degree of insulin resistance." (PMID 28814963, 2017). "If impaired insulin production was the main reason for increased GDM risk among carriers of the risk alleles of MTNR1B and GCK, this may explain why carriers of the risk alleles did not benefit as much as non-carriers from insulin resistance reduction due to lower fat consumption." (PMID 29340108, 2017). "Lowering the levels of FFA has been shown to increase insulin sensitivity in obese and non-obese diabetic subjects, indicating the important role of FFA in insulin resistance." (PMID 29209160, 2017). "We have demonstrated that consumption of low AGE diets decreased insulin resistance regardless of participants’ T2DM status and reduced fasting insulin levels in patients with T2DM as well as decreased total cholesterol in participants without T2DM." (PMID 28536448, 2017).
Insulin resistance (continued). "Homeostatic model assessment of insulin resistance revealed significant insulin resistance in HFD fed mice when compared with the ND groups, and FAD treatment improved insulin sensitivity (data not shown)." (PMID 29118818, 2017). "Gensini score was not correlated with insulin (fasting or post-prandial), HOMAIR (representing insulin resistance) or HOMAB (representing β cell function)." (PMID 29079813, 2017). "Therapies targeting postprandial glucose, including acarbose and insulin, prevent CVD in diabetic patients, whose beneficial effects are independent of improving insulin resistance." (PMID 29079813, 2017). "Consistent with the insulin resistance inherent in the HFD group, insulin did not induce a significant activation of Akt in this group." (PMID 28710347, 2017). "Second, insulin resistance was evaluated by the simple surrogate index of HOMA-R, which is not a direct quantitative index of insulin-mediated glucose uptake in skeletal muscles and/or adipose tissue." (PMID 29445750, 2017). "However, prolonged caloric excess invokes adaptive processes like storage of excess calories in the form of triglycerides, which eventually may have negative consequences (obesity, ectopic adipose deposits, insulin resistance, inflammation, and eventually impaired insulin secretion)." (PMID 29403436, 2017). "CML was significantly negatively correlated with insulin secretion, HOMA-%B, and IRI-AUC and positively correlated with ISI in T2DM participants but was not correlated with insulin resistance as evaluated by the glucose clamp method." (PMID 28695132, 2017). "This trend fits with the theory of RBP-4 being a marker of obesity, rather than insulin resistance, as GHR−/− mice are obese but insulin sensitive." (PMID 28670222, 2017). "Taken together, the results indicate that HFCS consumption has negative effect on insulin sensitivity, and ghrelin exerts a protective role in HFCS-induced inflammation and insulin resistance." (PMID 28629187, 2017). "Induction of insulin resistance by treating cells with a combination of high glucose and high insulin (HGHI) showed that cells lacking FNDC5 are not more resistant to insulin than control cells after 10 minutes insulin stimulation." (PMID 29176631, 2017). "In conclusion, our data show that ghrelin induces acute peripheral insulin resistance via mechanisms that are independent of GH, cortisol, and ambient serum FFA levels but does not impact on hepatic insulin sensitivity." (PMID 28198428, 2017). "In our study, there were no significant improvements of blood glucose, plasma insulin and HOMA-IR between T2D and T2D+PF groups after capsaicin exposure, which indicated direct beneficial effects of capsaicin on glucose metabolism and insulin resistance." (PMID 28225806, 2017). "Insulin levels and HOMA-IR did not correlate with BMI in these investigations, suggesting a link between gliosis, pancreatic responses and insulin resistance unrelated to the degree of adiposity." (PMID 28469281, 2017). "When adipocytes show insulin resistance, GLUT4 does not translocate to cell membrane in response to insulin release by the pancreas, and this leads to reduced glucose uptake." (PMID 28333091, 2017). "Although most of the patients did not have insulin resistance or T2DM, it is well known that raised systemic insulin levels can potentiate anabolic effects to mediate cell proliferation and enhance tumor growth." (PMID 27525640, 2017). "Compared with those without PD, Ob children with PD showed decreased insulin resistance-adjusted β-cell function as assessed by ISSI-2, reduced insulin sensitivity expressed as WBISI and QUICKI, and reduced disposition index calculated by IGI and WBISI." (PMID 29242622, 2017).
Insulin resistance (continued). "Therefore, from a physiological perspective, the ability of insulin to upregulate REDD1 expression in skeletal muscle could be envisioned as a regulatory loop to restore basal signalling, and/or as a contributing factor in the development of insulin resistance." (PMID 27613400, 2016). "In addition, since, as described in the methods, HOMA-R can represent insulin resistance in relatively low fasting blood glucose levels, where effects of GCs on insulin resistnace appear to be limited, the study might not have enough statistical power to evaluate association between GCs and HOMA-R." (PMID 27861636, 2016). "There was no improvement in insulin sensitivity (HOMA2 of insulin resistance [HOMA2-IR] and HOMA2 of insulin sensitivity [HOMA2-%S]) or beta cell function (HOMA2 of beta cell function [HOMA2-β])." (PMID 26350611, 2016). "However, in the db/db mouse model of insulin resistance, metformin dephosphorylates endogenous murine tau without affecting glycemia and metabolic parameters, suggesting that the effects on tau may be independent from the drug’s insulin-sensitizing action." (PMID 26858121, 2016). "LBW men had a higher hepatic insulin resistance index after the control diet compared with NBW men, but LBW and NBW men did not have a different insulin‐stimulated glucose infusion rate, M‐value, after this diet." (PMID 27694528, 2016). "Although plasma insulin levels also tended to be higher in the LCHFD fed mice, this was clearly not sufficient to overcome the insulin resistance in these mice." (PMID 26878317, 2016). "Our use of C-peptide level as a marker of insulin resistance, rather than the HOMAIR (using insulin and glucose measures), was justified as C-peptide is a validated marker of hyperinsulinaemia and has been previously associated with colorectal cancer risk." (PMID 27046222, 2016). "There did not exist a definite correlation between insulin resistance markers and such lipid markers as HOMA-IR, fasting insulin, insulin levels at the 2nd hour (data not shown)." (PMID 26439243, 2016). "Although we estimated rather than measured insulin resistance, our results suggest that, at least in diabetic CKD patients, over-correction of metabolic acidosis may also be detrimental since values of serum bicarbonate greater than 28 mEq/l are associated with decreased insulin sensitivity." (PMID 27770799, 2016). "The obese group presented significantly higher somatometric parameters (BW, BMI, and WC), FPG, insulin resistance (HOMA-IR), insulin secretion (II), and SFA, but a lower insulin sensitivity (OGIS) than the nonobese group (all p < 0.001)." (PMID 26788116, 2016). "Besides, a study conducted in obese children with- or without insulin resistance (homeostasis model assessment >4 or ≤4, respectively) demonstrated that body weight reduction contributed to lowering both cortisol levels and insulin resistance in the insulin-resistant group." (PMID 27478508, 2016). "Molecular links leading to TLR4-induced insulin resistance are not fully elucidated, but some studies mention that TLR4 signaling interferes with insulin signaling." (PMID 27105827, 2016). "The average fasting and 2-hour postprandial insulin values as well as the HOMA-IR and HOMA-β values indicated that, even in individuals who did not have T2D at baseline, there was a high likelihood of insulin resistance." (PMID 27896278, 2016). "Although adiposity is closely related to inflammation, our findings suggest that lean, insulin-resistant individuals could present higher levels of inflammatory biomarker even without excessive adipose tissue, compared with an overweight subject without insulin resistance." (PMID 26862350, 2016). "This study showed no relation between insulin sensitivity and ceramide or DAG content suggesting that ceramide and DAG are not major players in the early phase of insulin resistance in human muscle." (PMID 27777958, 2016).
Insulin resistance (continued). "This is because plasma insulin was not increased after PFJ supplementation in NRs, and another previous study also revealed that the early problem in NRs was insulin resistance with hyperinsulinaemia, not insulin insufficiency." (PMID 27795741, 2016). "Unlike the insulin resistance seen in Caucasians, Asian patients with T2DM have a relatively low BMI and a predominant insulin secretory defect." (PMID 26925169, 2016). "To examine the effect of PLIN5 on lipid-induced insulin resistance we overexpressed PLIN5 in rat skeletal muscle and observed a profound increase in intramyocellular LD content while insulin-stimulated glucose uptake was not impaired." (PMID 26864436, 2016). "Other findings in our study, such as differences between the obese and control groupsregarding insulin level and HOMA-IR, findings independent of blood glucose level, also support the importance of insulin resistance in the development of these pathologies." (PMID 26758313, 2016). "Lastly, we used fasting insulin and HOMA-IR to evaluate insulin resistance rather than the gold standard clamp technique." (PMID 26997950, 2016). "Plasma AGE levels of FruLys, 3-DF, 3-DPs, 3-DP, MGH1, 3-DGH, CML, CEL and MetSO were independent of fasting glycaemia as well as fasting insulin and HOMA-IR as a surrogate of insulin resistance." (PMID 26018950, 2015). "Mice often, but not always, develop insulin resistance with HGR diet-induced obesity, though these mice remained insulin sensitive after 14 wks of the HGR diet." (PMID 26030878, 2015). "Despite indication of insulin resistance in the ipITT of female mice treated with DEHP, HOMA-IR and serum triglyceride concentrations did not reflect impaired insulin sensitivity in unchallenged fasted animals." (PMID 26630026, 2015). "The study cohort included euglycemic overweight rhesus monkeys with insulin resistance in the absence of impaired fasting glucose (IFG) and age and weight pair-matched insulin sensitive controls." (PMID 26063458, 2015). "The data that liver but not WAT and muscle from the Ccny KO mice presented insulin resistance further support this observation at the cell-level, suggesting that CCNY is mainly required for the functional insulin signaling in mouse liver." (PMID 26161966, 2015). "The homeostasis model assessment-insulin resistance (HOMA-IR) and insulin sensitivity index (ISI) were not significantly different after GLP-1 analogue treatment (P = 0.343 and 0.570, resp)." (PMID 25785276, 2015). "We have shown that TUSC5 expression was reduced in insulin resistance, and although TUSC5 was not sufficient to overcome insulin resistance, TUSC5 was necessary for the full insulin-sensitizing effects of rosiglitazone." (PMID 26240143, 2015). "Insulin infusion can increase GLUT4 expression in the health persons, obese one with insulin resistance and type 1 diabetic patients, but not in type 2 diabetic patients." (PMID 25713812, 2015). "The positive correlation, in controls, of 6-OH-MEHP with insulin, and the HOMA index, and the negative correlation with the FGIR suggested that this metabolic pathway favoured insulin resistance." (PMID 25706863, 2015). "T2DM is a progressive spectrum of insulin resistance, with overt T2DM representing a state where insulin secretion, despite being elevated, is no longer sufficient to control blood glucose." (PMID 26682540, 2015). "In our study, hepatic insulin resistance, as calculated by HOMA-IR (derived from FPG and fasting plasma insulin concentrations), was not significantly different between patients with DM-NAFLD and those with T2DM only." (PMID 24397589, 2014).